IRF4 (interferon regulatory factor 4)
Diseases named in the same sentence as IRF4 in open-access papers (continued):
Sharing a sentence is not in itself a finding about the gene and the disease.
myeloma (continued). "For example, super-enhancer-associated genes include IRF4 and MYC in multiple myeloma, PAX5, MYC, and IRF4 in diffuse large B-cell lymphoma, MYCN and ALK in neuroblastoma, and CDK6, MYC, and EGFR in glioblastoma." (PMID 29724031, 2018). "Numerous studies have shown that c-MYC is essential for multiple myeloma cell survival and that IRF4 regulates its expression." (PMID 29346274, 2018). "Interferon regulator factor 4 (IRF4) is characterized to be a member of interferon regulatory family, which is predominantly expressed in bone marrow plasma cells of patients with multiple myeloma (MM)." (PMID 29156727, 2017). "The transcription factor IRF4, identified as an essential factor for myeloma cell survival, is involved in the activity of lenalidomide to treat multiple myeloma." (PMID 28894755, 2017). "IRF4 directly enhances MYC, and MYC enhances IRF4, generating an autoregulatory circuit in multiple myeloma." (PMID 28910419, 2017). "Here we further dissect the anti-myeloma mechanisms mediated by EZH2 inhibition and show that pharmacological inhibition of EZH2 reduces the expression of MM-associated oncogenes; IRF-4, XBP-1, PRDM1/BLIMP-1 and c-MYC." (PMID 28052011, 2017). "Abnormal activity of a number of transcription factors has been implicated in multiple myeloma development, including NF-κB, MAF, MYC, and interferon regulatory factor 4 (IRF4)." (PMID 26731516, 2016). "While oncogenic translocations of IRF4 have been found, more frequently, myeloma and other lymphoid malignancies are dependent on dysfunctional transcriptional networks downstream of a genetically normal IRF4 locus." (PMID 26731516, 2016). "Lenalidomide reduced in a dose-dependent manner IRF4 expression (measured by flow cytometry) in OPM2 myeloma cells (60% reduction with 10 μg/ml lenalidomide)." (PMID 27057635, 2016). "As a result, MYC is overexpressed following the translocations of its gene, which in turn induces overexpression of IRF4, thus forming a loop which helps the myeloma cells survive and grow." (PMID 28083618, 2016). "Since the regulation of the IRF4 transcriptional axis through small molecule inhibition of CBP/EP300 bromodomains would represent a promising new therapeutic strategy for multiple myeloma, we sought to better understand our initial observations." (PMID 26731516, 2016). "We noted in particular the significant negative correlation (p-value < 0.05) of 4 gene signatures containing downstream targets of IRF4, a lymphocyte-specific transcription factor that is essential for the survival of multiple myeloma cells." (PMID 26731516, 2016). "Given that TCF3 activates numerous proapoptotic genes, it is conceivable that tumor-suppressor effect does not depend on a single factor but develops as a “death by a thousand cuts” as it was supposed for IRF4 depletion in multiple myeloma." (PMID 27166193, 2016). "Through gene expression profiling and chromatin immunoprecipitation analysis, the Myc oncogene was demonstrated as a direct target of IRF4, and IRF4 was proposed as a master regulator of malignancy-specific gene expression in multiple myeloma." (PMID 27223072, 2016). "Here, the authors reveal a role for the histone demethylase KDM3A in the survival of this haematologic cancer, and show that mechanistically KDM3A removes H3K9 methylation from the promoters of KLF2 and IRF4, genes essential for myeloma cell survival." (PMID 26728187, 2016). "We have shown that CBP/EP300 bromodomain inhibition leads to viability defects in multiple myeloma cell lines and to the suppression of IRF4 and its downstream transcriptional programs in the representative cell line LP-1." (PMID 26731516, 2016).
myeloma (continued). "In myeloma cells, IRF4 is a major transcription factor for initiating plasma cell differentiation and Ikaros and Aiolos control IRF4 gene expression." (PMID 27057635, 2016). "Lenalidomide-induced IRF4 degradation in normal PBs and PCs is less pronounced than in OPM2 myeloma cells, possibly because IRF4 expression is deregulated in myeloma cells through continuous triggering by aberrant MYC expression." (PMID 27057635, 2016). "IRF4 is essential for the survival of multiple myeloma cells, indicating that the IRF4/Myc transcription pathway is being affected by CBP/p300 bromodomain inhibition." (PMID 29170712, 2016). "Since stable IRF4 depletion is cytotoxic for myeloma cells, these experiments were performed using transient infections." (PMID 26269456, 2015). "As a stimuli-independent positive control, we used whole cell lysates from a murine myeloma cell line P3X63Ag8 (termed P3XAg) that constitutively expresses IRF4." (PMID 24391506, 2014). "In 18 selected cancer types, the expression level of IRF4 was the highest in myeloma, followed by lymphoma, melanoma and leukemia." (PMID 25207815, 2014). "Together, these results indicate that IRF4 is overexpressed in specific hematological malignancies including myeloma, lymphoma, and leukemia, and also in melanoma." (PMID 25207815, 2014). "SPIB alone or in conjunction with PU.1 made only a minor contribution to IRF4 occupancy in H929 myeloma cells." (PMID 24875472, 2014). "Equally, EICEs were recovered from sites occupied by IRF4 and SPIB or PU.1 and at sites occupied by IRF4 and PU.1 in the H929 myeloma." (PMID 24875472, 2014). "In brief, human myeloma lines depend for their survival on IRF4, which, through a caspase 10-dependent mechanism, prevents excessive autophagy from executing non-apoptotic myeloma cell death." (PMID 24659989, 2014). "IRF4 is also important in the pathogenesis of multiple myeloma, and is involved in EBV mediated growth transformation of B-lymphocytes." (PMID 23658517, 2013). "The Interferon Regulatory Factor 4 (IRF4) gene encodes a transcription factor important for key developmental stages of hematopoiesis, with known oncogenic implications in multiple myeloma, adult leukemias and lymphomas." (PMID 23977280, 2013). "Recently, it was reported that inhibition of IRF4 is deleterious to myeloma cell lines suggesting that IRF4 silencing can be a potentially new target to be exploited therapeutically." (PMID 23658517, 2013). "Despite functioning as a tumor suppressor gene in early B-cell development, IRF4 is a well-established oncogene in multiple myeloma (MM), with oncogenic implications extending to certain adult lymphomas and leukemias." (PMID 23977280, 2013). "For drug screening purposes we were most interested in analyzing the myeloma survival factor IRF4 since our translational laboratory focuses on this disease." (PMID 22984542, 2012). "Due to potential therapeutic use in our patient population we were most interested in identifying small molecule inhibitors of the multiple myeloma survival factor IRF4." (PMID 22984542, 2012). "Most HIV-related HL cases express LMP1 and display the BCL6-/CD138+/MUM1 IRF4+ (for Multiple Myeloma-1 Interferon Regulatory Factor-4), phenotype, thus reflecting post-GC B cells." (PMID 20936156, 2011). "Moreover, in multiple myeloma (MM), IRE1α regulates phosphorylation of Interferon regulatory factor 4 (IRF4), a key transcription factor for tumor cell proliferation." (PMID 41372991, 2025). "Moreover, the cytoplasmic region of CD86 is important for triggering molecular changes, such as the upregulation of Interferon regulatory factor 4 and Integrin beta-1 in myeloma cells." (PMID 38251379, 2024). "IRF4 inhibition enhanced the sensitivity of myeloma cells to standard cancer therapeutic agents." (PMID 38130025, 2024).
myeloma (continued). "Degradation of Ikaros and Aiolos leads to suppression of interferon regulatory factor 4 (IRF4), a transcription factor critical for myeloma survival, as well as elevation of IL-2, an enhancer of natural killer cells, which supports attack on cancer cells and, thereby, inhibits tumorigenesis." (PMID 37238617, 2023). "Moreover, we describe the unique role of IRF4 in acute leukemias and B cell mature neoplasia, focusing on pathogenetic implications and possible therapeutic strategies in multiple myeloma and chronic lymphocytic leukemia." (PMID 36495369, 2023). "IRF4, another midnolin substrate, is a lineage-specific transcription factor that is essential for the function and homeostasis of mature B and T cells and is an oncogenic driver of multiple myeloma." (PMID 37616343, 2023). "IRF4 is necessary for the survival of myeloma cells, and the deletion of IRF4 is lethal." (PMID 35740562, 2022). "Furthermore, dual G9a and EZH2 inhibition reduces myeloma cell proliferation by modulating the interferon signal and the IRF4-MYC axis." (PMID 35409271, 2022). "Myeloma cells are addicted to several proteins like c-Myc, IRF4, and IKZF1." (PMID 35646666, 2022). "Myelocytomatosis oncogene (MYC) is a direct target of IRF4 in activated B cells and myeloma." (PMID 36045700, 2021). "Some genes do manifest this type of selectivity (e.g., broad dependence on CTNNB1 in colorectal cancer, MYB in leukemia, IRF4 in multiple myeloma, KRAS in pancreatic cancer, and SOX10 in skin cancer), but such common essentiality within a lineage is relatively unusual." (PMID 33554860, 2021). "Moreover, HDAC11 accomplishes this through direct interaction with the IRF4 transcription factor, which has a well-established role in controlling B cell and plasma cell differentiation as well as myeloma genesis." (PMID 34793338, 2021). "Moreover, it was shownthat prolonged G1 arrest would diminish anti-apoptoticproteins like IRF4, which protecting myeloma cells fromapoptosis or decreasing chemo-resistance." (PMID 31606963, 2020). "The IRF4 ASOs are chimeric gapmer nuclease-resistant oligonucleotides with constrained ethyl chemistry that have high affinity, stability, and tolerability; and are currently in multiple myeloma clinical trials." (PMID 32859220, 2020). "The IRF4 ASO has advanced into a clinical trial in multiple myeloma (NCT04398485)." (PMID 32859220, 2020). "Conversely, the top-200 genes that negatively correlated with TOX exhibited significant overlap with post-GC B-cell signatures, including down-regulated signatures in FL (compared to reactive lymph node or NMZL either), IRF4 programme in myeloma and plasma cells and MYD88 up-regulated transcriptome." (PMID 32106280, 2020). "IRF4 is a key regulator at multiple steps in B-cell differentiation and development and is an oncogene in multiple myeloma, to a lesser degree in Hodgkin and non-Hodgkin lymphomas as well as in chronic lymphocytic leukemia." (PMID 32014112, 2020). "This suggests that c-MYC/IRF4/miR-125b interplay could be less effective in NB compared with multiple myeloma in terms of MICA induction." (PMID 31040907, 2019). "Moreover, anti-myeloma activity was achieved via direct downregulation of IRF4 and its downstream effector BLIMP-1." (PMID 31009917, 2019). "Interestingly, a synthesis-dependent IRF4 activity was shown to protect myeloma cells in human patients." (PMID 31134075, 2019). "They include diffuse large B cell lymphoma (DLBCL), follicular lymphoma (FL), Burkitt’s lymphoma, mixed FL/DLBCL lymphomas, primary mediastinal large B cell lymphoma, multiple myeloma, IRF4-rearranged large cell lymphoma, MYC-negative Burkitt-like lymphoma with chr." (PMID 31039827, 2019). "The immune system plays an important role in growth of myeloma cells, but the mechanisms controlling T helper cell lineage by IRF4 in MM is unknown." (PMID 29156727, 2017).
myeloma (continued). "Interestingly, while oncogenic translocations of IRF4 have been found, myeloma and other lymphoid malignancies are more frequently dependent on dysfunctional transcriptional networks downstream of a genetically normal IRF4 locus." (PMID 27903272, 2016). "We reasoned that CBP/EP300 bromodomain inhibition may exert its phenotypic effects through the suppression of MYC downstream of IRF4 in multiple myeloma cells." (PMID 26731516, 2016). "Interestingly, a recent RNA-inference-based genetic screen revealed that IRF4 function is required for myeloma cell line survival as inhibition of the gene proved toxic to the malignant cells, an in vitro finding supporting the genes role in pathogenesis." (PMID 24803933, 2014). "For this analysis we used A20, a mature B cell line known to secrete basal IL-10, BCL-1-3B3 cell line, a leukemic cell line that can be differentiated in vitro to plasma cells, and P3X63Ag8, a mouse plasmacytoma/myeloma cell line that expresses high levels of endogenous IRF4." (PMID 24391506, 2014). "Lenalidomide inhibits the translation of C/EBPβ by downregulating eIF4E, and IRF4 downregulation has been reported to be a critical factor controlling multiple myeloma survival and as a prognostic marker in patients with multiple myeloma associated with poor survival." (PMID 23420263, 2013). "IRF4 is associated with enhanced pathogenesis of EBV-mediated growth transformation of B-lymphocytes, and has been shown to play a primary role in cell proliferation of multiple myeloma." (PMID 23658517, 2013). "Using IRF4 expression inhibition as an endpoint for drug candidate identification we found agents that at least in preliminary screens appear to possess selective actions against multiple myeloma cells." (PMID 22984542, 2012). "Silencing during differentiation of CD34 positive cord blood cells closed respective chromatin while treatment of myeloma cells with an IRF4 transcriptional inhibitor opened a site to DC-PCR that was occupied by RNA polymerase II and NFκB as determined by ChIP." (PMID 22984542, 2012). "The transcription factor IRF4, highly and constantly expressed in antibody producing plasma cells and their malignant counterpart multiple myeloma but otherwise limited to lymphoid and myeloid cells where it is mostly expressed in response to stimuli, is such an example." (PMID 22984542, 2012). "In contrast, we have demonstrated that the selective inhibition of HDAC11 promoted the deacetylation of IRF4 — a vital signal pathway essential to the biology and oncogenic mechanism of plasma cell myeloma — and may provide a more effective translational strategy." (PMID 34793338, 2021). "Interestingly, motif analysis of enhancer H3K27ac by ChIP-Seq implicated the Ets family TF FLI1 as an additional candidate for a regulator of cellular enhancers in PEL, reminiscent of the recently reported cooperation of FLI1 with IRF4 on SEs in multiple myeloma." (PMID 32843547, 2020). "Knocking down of IRF4 could cause the rapid death of MM cells, prompting IRF4 is a characteristic expression of myeloma cells, and the dysregulation of IRF4 could contribute to malignant transformation, indicating IRF4 is also a precursor state for the development of MM." (PMID 29156727, 2017). "Reduced expression of IRF4 in people carrying the rs872071 G allele should lead to reduced expression of BLIMP-1, which, given the function of BLIMP-1 as a MYC repressor, could help in abnormal growth of MYC expression during the formation of multiple myeloma." (PMID 28083618, 2016). "Taken together, these data suggest that the bromodomains of CBP and EP300 are involved in the regulation of the IRF4/MYC axis in multiple myeloma cells, and the suppression of the IRF4/MYC axis may be important for the phenotypic effects of CBP/EP300 bromodomain inhibition." (PMID 26731516, 2016).
myeloma (continued). "IRF4 overexpression is a hallmark of the activated B-cell-like (ABC) type of diffuse large B-cell lymphoma (DLBCL) and multiple myeloma (MM), and is also overexpressed in almost 100% cases of classical Hodgkin lymphoma (cHL), plasma cell myeloma and primary effusion lymphoma (PEL)." (PMID 25207815, 2014). "PC4 expression is positively regulated by IRF4 and forms a complex with IRF4 and IKAROS—a target of lenalidomide-directed degradation in multiple myeloma—which promotes B cell differentiation into ASCs." (PMID 39708811, 2025). "It is 7–12 times more effective at suppressing multiple myeloma cell growth and 6–15 times more potent at inhibiting the NF‐κB, PI3K/AKT, JAK/STAT3, and IRF4 pathways than curcumin." (PMID 39945243, 2025). "This ultimately leads to downregulation of interferon regulatory factor 4 (IRF4) and c-MYC, which are critical for myeloma cell survival." (PMID 40227746, 2025). "Mechanistically, mSWI/SNF ATPase degrader treatment in multiple myeloma cells compacted chromatin, dislodged POU2AF1 and IRF4, and decreased IRF4 signaling." (PMID 38328238, 2024). "Western blot showed IRF4 degraded faster in myeloma cells treated with TAK-981 compared to vehicle, indicating SUMOylation inhibition decreased IRF4 protein level through enhancing degradation." (PMID 35338347, 2023). "In myeloma cells sourced from obese patients, ACSS2 is regulated by adipocyte‐secreted angiotensin II, where it stabilizes interferon regulatory factor 4 (IRF4) through acetylation, thereby upregulating IRF4‐controlled gene expression." (PMID 38034101, 2023). "IRF4 activate c-Myc expression, and IRF4 was itself a direct target of MYC transactivation, generating an autoregulatory circuit in myeloma cells." (PMID 35338347, 2023). "Adipocyte-derived angiotensin II stimulated ACSS2 expression in myeloma cells, while upregulated ACSS2 interacted with the oncoprotein interferon regulatory factor 4 (IRF4) to enhance the its stability and expression by mediating its acetylation." (PMID 35798917, 2022). "Degradation of Ikaros and Aiolos by lenalidomide and pomalidomide leads to specific and sequential downregulation of c-Myc followed by interferon regulatory factor 4 (IRF4), which results in subsequent cell death of myeloma cells." (PMID 36311747, 2022). "B‐cell progenitor fate determinant interferon regulatory factor 4 (IRF4) exerts key roles in the pathogenesis and progression of multiple myeloma (MM), a currently incurable plasma cell malignancy." (PMID 35544413, 2022). "Specifically, SuperDendrix finds associations between increased dependency on the transcription factor TCF3 and the mutually exclusive set {myeloma, BCL2(A)} and the transcription factor IRF4 and {myeloma, lymphoma}." (PMID 35382456, 2022). "IRF4 is also a direct target of MYC, generating an auto-regulatory circuit to support myeloma cell survival." (PMID 34680233, 2021). "Critically, IRF4 was itself a direct target of MYC transactivation, generating an autoregulatory circuit in myeloma cells." (PMID 36045700, 2021). "Collectively, our findings suggest that HDAC11 interacts with the IRF4/BLIMP1/MYC transcriptional network, which is critically dysregulated in myeloma genesis, and HDAC11 inhibition offers a potential therapeutic strategy for MM treatment." (PMID 34793338, 2021). "In multiple myeloma cells, CBIs raise the levels of the NK-activating ligands MICA and PVR through cereblon-dependent degradation of IKZF-1/3 and IRF4." (PMID 33411730, 2021). "CD86 overexpression induces molecular changes such as increased expression of integrin ß1 and ß7 and interferon regulatory factor 4 (IRF4), a transcription factor necessary for myeloma survival which directly targets MYC." (PMID 33634031, 2020). "Regarding the various biological roles ascribed to the FOXM1 in MM, it resembles some well-recognized transcription factors of myeloma, such as myelocytomatosis oncoprotein (MYC) and interferon regulatory factor 4 (IRF4)." (PMID 32679860, 2020).